NR2F1 (nuclear receptor subfamily 2 group F member 1)
Diseases named in the same sentence as NR2F1 in open-access papers (continued):
Sharing a sentence is not in itself a finding about the gene and the disease.
tumor (continued). "NR2F1 also assumed an important role in shaping the tumour microenvironment of BC, which indicated that NR2F1 is a potential biomarker for predicting the efficacy of immunotherapy for BC." (PMID 39219375, 2024). "NR2F1 overexpression successfully inhibited the proliferation capacity of MMTV-MYC tumor cells obtained from the MMTV-MYC transgenic mouse model characterized by enforced c-MYC expression." (PMID 38418814, 2024). "The activation of the NR2F1 gene can occur during epigenetic chemotherapy, giving tumor cells the ability to form latent phenotype." (PMID 38418814, 2024). "The transcriptional regulator NR2F1 is known as a potential clinical marker of dormant cancer cells, and quiescent disseminated tumor cells (DTCs) of different cancers can be found using NR2F1 antibodies." (PMID 38418814, 2024). "The depletion of macrophages significantly reduced NR2F1 levels in the tumor cells and prevented dormancy." (PMID 38659591, 2024). "The current research has demonstrated that agonists of NR2F1 can induce cancer cell dormancy to inhibit tumor metastasis." (PMID 38103068, 2023). "Given the involvement of NR2F1 in the modulation of transcriptional processes during tumor cell dormancy, we further explored its transcriptional regulatory role in GBM cells." (PMID 37968257, 2023). "Though NR2F1-positive and SOX9High cancer cells constitute a very small percentage of the primary tumor, they both become enriched as tumor cells approach TMEM doorways, enter the bloodstream, and finally arrest in the lung." (PMID 35110548, 2022). "As expected, our analysis revealed an enrichment (~3.2-fold) of double MenaINV-positive and NR2F1-positive tumor cells at TMEM doorways (0–80 μm), compared to tumor cells farther away (160–200 μm) (blue curve)." (PMID 35110548, 2022). "When co-cultured cells were separated by a 0.4 μm porous membrane, we observed a similar increase in tumor cell NR2F1 expression in the presence of macrophages, indicating that soluble factors are responsible for the induction of NR2F1." (PMID 35110548, 2022). "Analysis of these distances revealed an ~2.2-fold enrichment of NR2F1-positive tumor cells near TMEM doorways (0–80 μm), compared to tumor cells farther away (160-200 μm) (red curve)." (PMID 35110548, 2022). "An important question that remains to be elucidated is the molecular mechanism by which macrophages induce the expression of NR2F1 in tumor cells, but this investigation is beyond the scope of our current study." (PMID 35110548, 2022). "This high level of NR2F1 DTC positivity was also found in disseminated tumor cells in the lung tissue (left “Lung” bar)." (PMID 35110548, 2022). "Cancer immune activity measured by interferon (IFN)-γ response, fractional change, and tumor-infiltrating lymphocytes (TIL) fraction were all significantly lower in the NR2F1-high tumors in TCGA." (PMID 35740627, 2022). "NR2F1 is a known marker of tumor dormancy and is expressed higher in dormant cell lines and bone metastatic clone cells." (PMID 35740627, 2022). "Given our observation that the expression of MenaINV and NR2F1 in tumor cells are both increased near TMEM doorways, we sought to determine if both proteins are mechanistically linked, or independently regulated." (PMID 35110548, 2022). "NR2F1 has been demonstrated to contribute to cancer cell dormancy, as well as to be a potential impact on tumor recurrence and metastasis." (PMID 35395809, 2022). "We then quantified the percentage of NR2F1-positive tumor cells in primary tumors, CTCs, and lung tissues from an E0771-GFP SM model." (PMID 35110548, 2022). "Given that cell growth arrest is the major characteristic of tumor dormancy, it was of interest to investigate the relationship between NR2F1 expression and cell proliferation." (PMID 35740627, 2022).
tumor (continued). "We found that, while downregulation of NR2F1 limits the extravasation ability of tumor cells by ~10%, still ~25% of the DTCs with knockdown are able to extravasate, suggesting a minor role for NR2F1 on this step." (PMID 35110548, 2022). "This indicates that NR2F1 and MenaINV are, to some extent, dependently regulated within tumor microenvironment, although we cannot conclude from these data that Mena directly regulates NR2F1." (PMID 35110548, 2022). "We observed an ~2-fold enrichment of NR2F1-positive tumor cells in close proximity (0-40 μm) to macrophages in primary tumors." (PMID 35110548, 2022). "All these results indicated that NR2F1 expression was associated with suppressed cell proliferation, which agrees with the notion that NR2F1 is a tumor dormancy marker." (PMID 35740627, 2022). "We found that NR2F1 expression is significantly increased in tumor cells co-cultured with macrophages compared to tumor cells cultured alone (48% vs. 10%), or co-cultured with endothelial cells (16% vs. 10%)." (PMID 35110548, 2022). "NR2F1 is a known tumor dormancy marker, and RARβ and TGF-β signaling have been reported to induce dormancy." (PMID 35740627, 2022). "We also observed numerous instances of NR2F1-positive tumor cells located inside the lung vasculature." (PMID 35110548, 2022). "Using digital whole slide scanning and tissue alignment software, we were able to co-register the two slides down to the single-cell level and measure the relative distance from each NR2F1-positive tumor cell to the nearest TMEM doorway." (PMID 35110548, 2022). "NR2F1 serves as a critical node in the induction and maintenance of tumor stem cell dormancy by integrating epigenetic programs of quiescence and survival." (PMID 36028490, 2022). "Because of this pleiotropic regulation and proliferation suppression, NR2F1 has been identified as a master regulator of tumor dormancy." (PMID 35740627, 2022). "Early reports of the successful development of an effective specific agonist of the tumour dormancy-regulating orphan nuclear receptor NR2F1 have provided an exciting indication of the potential for such targeted therapeutics." (PMID 34439077, 2021). "In this context, it has been demonstrated that dormant cells arise from the primary tumor in specific hypoxic niches by the activation of genes like Nr2f1 and promote heterogenicity." (PMID 32028565, 2020). "This is further supported by our findings that BHLHE41 or NR2F1 knock down strongly stimulated tumor take and growth of MCF-7 ER+ luminal cancer cell lines during the initial dormancy phase that precedes logarithmic tumor growth." (PMID 22530051, 2012). "The COUP-TF1 gene (Nr2f1) was upregulated in transgenic and tumor in comparison to the normal tissue according to gene expression measurements (fold changes 6.26 and 2.62 in transgenic and tumor, respectively)." (PMID 21464922, 2011). "Moreover, IF showed that the number of NR2F1+ dormant cells in mice treated with tozasertib increased significantly, while the positive rate of Ki-67 in tumor cells decreased." (PMID 41408408, 2025). "Potentially, targeting NR2F1 and mTOR in both compartments, i.e., the tumor and TME, may amplify the therapeutic effect of future targeted inhibitors." (PMID 40955667, 2025). "Importantly, our findings show that a triple combination of BRAFi + MEKi + mTORi inhibited the survival of NR2F1-overexpressing cells in vivo and decreased tumor regrowth rates from MRD, suggesting that mTORi delays tumor growth of DTP cells." (PMID 40955663, 2025). "While additional dormancy markers such as p27^Kip1, NR2F1, or gene expression signatures have been shown to characterize this state; these are often context-specific and may vary by tumor type or experimental model." (PMID 40430044, 2025). "Since drug-tolerant cells may also gain motility and interact with the extracellular matrix to promote disease progression, we investigated how NR2F1 influences tumor invasion." (PMID 40955663, 2025).
tumor (continued). "NR2F1 overexpression minimizes tumor inhibition effects by BRAFi and MEKi treatment." (PMID 40955663, 2025). "As our understanding of tumor heterogeneity and the microenvironment deepens, disrupting the NR2F1 axis may offer a path to more durable remissions." (PMID 40955667, 2025). "Additionally, the results indicated a significant decrease in serotonin and related molecules, accompanied by the restoration of ALDOC and NR2F1 expression, in addition to the inhibition of tumor growth." (PMID 38741139, 2024). "Additionally, in vivo experiments showed that NR2F1 upregulation reversed the suppression effects of LINC00663 silencing on tumour growth, inflammation, and angiogenesis." (PMID 39219375, 2024). "However, overexpression of NR2F1 nullified the inhibitory effect of LINC00663 knockdown on tumour growth (#p < 0.05)." (PMID 39219375, 2024). "In summary, silencing LINC00663 repressed tumour growth by reducing NR2F1 expression." (PMID 39219375, 2024). "NR2F1 or Coup-TF1 (nuclear receptor subfamily 2, group F, member 1) is an orphan nuclear receptor of the retinoic acid receptor family, known as a tumor dormancy marker, which is downregulated in cancer to promote cell proliferation and metastasis by inducing the epithelial–mesenchymal transition." (PMID 36661515, 2023). "Our results support the valuable role of NR2F1 in tumor suppression." (PMID 37612452, 2023). "In tissue and CTCs from both metastasis models, we could find single tumor cells (GFP+) that expressed nuclear NR2F1." (PMID 35110548, 2022). "In the primary tumor, we observed only a small population (4%) that co-expressed NR2F1 and SOX9." (PMID 35110548, 2022). "We also found that NR2F1 is most strongly expressed in cancer-associated fibroblasts (CAFs) and not in cancer cells in the tumor microenvironment (TME)." (PMID 35740627, 2022). "Furthermore, NR2F1 has been shown to regulate tumor dormancy in different mouse models, including breast cancer." (PMID 35110548, 2022). "In these cases, while NR2F1 is associated with cancer cell dormancy, DNAJB4 acts as a suppressor for cancer cell metastasis and STON2 negatively modulates tumor stemness and tumorigenesis." (PMID 34722496, 2021). "NR2F1 was found to control tumor cell dormancy via SOX9 and RARβ-driven quiescence programs." (PMID 33987095, 2021). "Our previous study has demonstrated that atRA treatment could also drive tumor dormancy of SACC by upregulating NR2F1." (PMID 33990215, 2021). "In addition, SACC specimens were simultaneously immunostained for NR2F1, relevant to tumor dormancy." (PMID 33990215, 2021). "The direct correlation between ZEB2 and NR2F1 transcripts is recurrently detected in the luminal tumor samples from all the microarray datasets interrogated in this study whereas it shows a less consistent pattern in the case of samples from basal subtype tumors (brown bars)." (PMID 30087437, 2019). "In addition, NR2F1, an orphan nuclear receptor, has been confirmed to induce quiescence of disseminated tumor cells." (PMID 28169357, 2017). "Besides, NR2F1 protein is a known tumour dormancy marker that promotes quiescence of various cancer cells, predominantly expressed in cancer‐associated fibroblasts, suggesting that it may intervene in the ENCC migration." (PMID 36738110, 2023). "To this end, we took lung tissues from the SM model, stained them for NR2F1 and MenaINV expression, and quantified the percent of single and double-positive tumor cells in single DTCs and in small (≤10 tumor cells), medium (11–300 tumor cells), and large (≥300 tumor cells) micro-metastases." (PMID 35110548, 2022). "However, it is still unknown what impact this downregulation has on the ability of tumor cells to extravasate, or whether cells with downregulated NR2F1 are immediately able to begin proliferating in the lung." (PMID 35110548, 2022). "In addition to the predominance of p38 activity, NR2F1 also regulates tumour cell dormancy." (PMID 34975909, 2021).
tumor (continued). "This upregulation, in turn, increases the expression of the downstream target gene nuclear receptor subfamily 2 group F member 1 (NR2F1), thereby promoting cell proliferation, invasion, inflammatory responses, and tumor angiogenesis." (PMID 40508012, 2025). "Consistently, biomarkers associated with cell dormancy as well as stemness were upregulated in tumor cells expressing high levels of TRAF4; however, their expression, including DEC2, SOX9, NR2F1, and P27, declined in cells expressingTRAFA‐P12A." (PMID 39716976, 2025). "We also observed an increase in dormancy markers NR2F1 and CDKN1B and a slowing of proliferation and tumor growth in vivo with GRHL2 overexpression." (PMID 39199676, 2024). "The findings showed that AHNAK, POLE2, SHMT2, NR2F1, and TFRC expression in tumor tissues was substantially higher than in normal tissues (P < 0.05)." (PMID 38103068, 2023). "Here, we expand this work with the finding that the primary tumor induces the expression of both NR2F1 and SOX9 in disseminating tumor cells that are in the vicinity of TMEM doorways." (PMID 35110548, 2022). "Lung tissue from EM and SM models, primary tumor tissues, and CTCs from the SM model were stained for GFP, NR2F1, SOX9, and DAPI." (PMID 35110548, 2022). "(iv) The direct correlation observed between the abundance of the NR2F1 and ZEB2 mRNAs in human tumor samples when using coexpression matrix analyses." (PMID 30087437, 2019). "Here, DNA binding activity at gene specific promoters of Xlr, Nr2f1, Zbtb7b, Sprr2i, Ffg18 and ERBB3 was observed with nuclear extracts of transgenic and tumor bearing mice but the overall activity varied considerably with no obvious trend." (PMID 21464922, 2011). "It is currently unknown whether macrophages in general, and whether macrophage-tumor cell interactions around TMEM doorways more specifically, are able to regulate NR2F1 expression on cancer cells." (PMID 35110548, 2022). "Our findings suggest that the NR2F1 gene expression signal from a patient’s bulk tumor is not from the cancer cells." (PMID 35740627, 2022). "The novelty of our study is that it is CAFs, not cancer cells, that are the dominant source of NR2F1 expression in the bulk tumor." (PMID 35740627, 2022). "The co-expression of NR2F1 (a dormancy marker) and SOX9 (a dormancy and cancer stem cell marker) preferentially in SM tumor cells suggests that these cancer cells adopt both dormant and cancer stem cell properties, a unique biology associated with the SM process." (PMID 35110548, 2022). "Despite high NR2F1 tumors showing tumor dormancy traits consistently, NR2F1 expression was not related to survival or distant metastasis." (PMID 35740627, 2022). "To this end, we believe that NR2F1 expression in the bulk tumor does not reflect expression in cancer cells; thus, its value as a biomarker is in doubt." (PMID 35740627, 2022). "Notably, the tumor groups showed a low expression level of HEY1 and NR2F1 compared with the normal group." (PMID 34457116, 2021). "The BCPRS-related genes (YY1, POU5F1, NKX2-3, NR2F1, HEY1, and IFNA13) showed high heterogeneity in different cells; thus, the genes can independently predict cellular composition to reflect the microenvironment of tumor tissues." (PMID 34457116, 2021). "Additionally, NR2F1 induces global chromatin repression by activating the pluripotency gene NANOG, which contributes to the dormancy of disseminated tumor cells in the bone marrow." (PMID 34064392, 2021). "(iii) The inverse correlation found between the abundance of the NR2F1 mRNA and the transcripts for other signaling elements of the pathway under analysis in this work (VAV2, VAV3, and CDH1) in human tumor samples according to in silico coexpression matrix analyses." (PMID 30087437, 2019).
tumor (continued). "The transcription factors include NR2F1/COUPTF173,74, BHLHE41/Dec2/Sharp-114,73 and FOXM172,73, which may serve as a “switch” for converting active tumor cells into “dormant” cells." (PMID 31819067, 2019). "We found that 12 days after tumor cell injection only 40% of the mice injected with control siRNA-treated cells had palpable tumors, while palpable tumors were present in 100% of the mice injected with BHLHE41 or NR2F1 siRNA treated cells." (PMID 22530051, 2012). "Moreover, contact with macrophages activated in tumor cells expression of stem-like SOX-9 phenotype and Nuclear Receptor Subfamily 2 Group F Member 1 (NR2F1), the orphan nuclear receptor and one of the best molecular markers of dormancy that regulates expression of pluripotency genes." (PMID 38659591, 2024). "However, to confirm that the induction of NR2F1 is due to macrophage-tumor cell and not macrophage-endothelial cell interactions, we co-cultured tumor cells with macrophages or with endothelial cells and stained them for NR2F1." (PMID 35110548, 2022). "Taken together, our current work demonstrates that both NR2F1 and MenaINV expression in tumor cells is induced by contact in the primary tumor with macrophages at TMEM doorways, similar to our recent finding that macrophages in the primary tumor program DTCs for stemness." (PMID 35110548, 2022). "In addition, our study also identified NR2F1, DNAJB4, and STON2 as the downregulated genes in SN, which could suppress tumor growth and metastasis." (PMID 34722496, 2021). "Although genetic changes may affect the level of mRNA expression, the findings of this study showed no significant variation in tumor copy number and nucleotide mutations of the six IMAAG genes (HEY1, IFNA13, NKX2-3, NR2F1, POU5F1, and YY1)." (PMID 34457116, 2021). "This implies that HEY1 and NR2F1 may be correlated with a malignant tumor progression phenotype rather than a tumorigenesis phenotype." (PMID 34457116, 2021). "Furthermore, the tumors produced by BHLHE41 and NR2F1 siRNA treated MCF-7 cells appeared to proliferate faster; the final tumor volume at day 12 was significantly larger for tumors produced by BHLHE41 and NR2F1 siRNA treated cells compared to those produced by control siRNA treated cells." (PMID 22530051, 2012).